RPS4XP2 (ribosomal protein S4X pseudogene 2)
Synonyms: dJ189G13.2; RPS4L2; RPS4P2; RPS4Y_2_1680
Gene: Transcribed processed pseudogene on chromosome 20 (4,629,427 to 4,630,219, reverse strand). Ensembl gene ENSG00000226948.
Diseases named in the same sentence as RPS4XP2 in open-access papers:
RPS4XP2 is named in the same sentence as 1 disease in open-access papers, as found by Europe PMC text mining. Sharing a sentence is not in itself a finding about the gene and the disease. The quoted sentences say what the papers report.
glioma (2 papers, 2017 to 2021). A benign or malignant brain and spinal cord tumor that arises from glial cells (astrocytes, oligodendrocytes, ependymal cells). "A 20-gene signature was identified, which was associated with radiotherapy.Furthermore, a novel 5-gene signature (HOXC10, LOC101928747, CYB561D2, RPL36A and RPS4XP2) as an independent predictor of glioma patients’ prognosis was further derived from the 20-gene signature." (PMID 29179492, 2017).